GBP5 (guanylate binding protein 5)
Diseases named in the same sentence as GBP5 in open-access papers (continued):
Sharing a sentence is not in itself a finding about the gene and the disease.
cancer (continued). "In addition, GBP5 has been shown to enhance tumor immunogenicity and has the potential to be a target for cancer immunotherapy." (PMID 36246628, 2022). "This study aims to explore the effect of GBP5 on immunity in pan-cancer." (PMID 36246628, 2022). "KEGG enrichment showed DEGs is enriched in oxidative phosphorylation and cell cycle, which may reveal the mechanism of GBP5 in cancer." (PMID 36246628, 2022). "In addition, we analyzed the differential expression of GBP5 in pan-cancer and found that in most cancer types (22/31), GBP5 expression in tumor tissues was higher than that in normal tissues." (PMID 36246628, 2022). "We found that GBP5 is elevated in a variety of cancers as a potential immunotherapy target." (PMID 36246628, 2022). "Overall, we have demonstrated in multiple ways that GBP5 plays a role in TME of multiple cancers." (PMID 36246628, 2022). "So far, most of what is known about GBP-5 in cancers is strictly correlative." (PMID 35681772, 2022). "The role of GBP5 on cancer stem cells requires more study to be elucidated." (PMID 34439200, 2021). "Importantly, the signature of combining high-level GBP5 and PI3K_AKT_MTOR gene set predicted a prolonged time interval for cancer progression in TNBC patients from the TCGA database." (PMID 33809079, 2021). "Moreover, we found that GBP5 modulated cell cycle, invasion/migration, and cancer stemness in OSCC cells." (PMID 34439200, 2021). "Considering GBP5 also took parts in innate immune activation and the regulation of inflammasomes related to cancer, its overexpression might be defensively activated in lesion when poor differentiation arose in GC cells." (PMID 34247602, 2021). "Except for GBP1 and GBP2, the role of other GBPs, including GBP5, in the malignant evolution of cancers, particularly TNBC, remains unclear." (PMID 33916322, 2021). "In the iC3 subtype, which was associated with the most aggressive SKCM cases, FAM135B gene mutation frequencies were increased, while CD8A, GBP5, KIAA0040, and SAMHD1 expression were downregulated, suggesting that these genes play important roles in cancer development and immune responses." (PMID 32639949, 2020). "However, there is limited research on GBP5 in the context of cancer." (PMID 38817865, 2024). "Nevertheless, the role of GBP5 in cancers, especially in OSCC, is still unknown." (PMID 34439200, 2021). "Additionally, we found that silencing GBP5 may decrease cancer stemness and enhance chemotherapy-induced apoptosis of SAS cells." (PMID 34439200, 2021). "IFITM3 and GBP5 both act as downstream factors of the IFN-γ/STAT1 pathway and can serve as cancer biomarkers." (PMID 40909948, 2025). "Guanylate-binding protein 5 (GBP5) increases sensitivity to this drug, and its removal consequently leads to increasing the required concentration of paclitaxel to kill cancer cells." (PMID 40869430, 2025). "In this study, we analyzed the relationship between GBP5 and clinical indicators or TME in pan-cancer." (PMID 36246628, 2022). "Overall, we found that for three genes, GBP5, LINC00707 and SLC4A11, the BPA effect on the expression is substantially smaller compared to the effect observed as a consequence of cancer." (PMID 34062972, 2021). "The results demonstrated that the expression of GBP1 and GBP5 were higher in HNSCC tissues, while the expression level of GBP6 was lower in cancer tissues." (PMID 32269280, 2020). "Conversely, some genes that displayed anti-HIV activity are known to be involved in signaling, both in various cancers (CD164, TNFRSF10A/D, ZWINT, MT1X, IL3) and immune or T cell activation (GBP5, CD1A)." (PMID 25980612, 2015). "In summary, although it is not closely related to some clinical parameters, GBP5 has the potential to be a prognostic biomarker for a variety of cancers." (PMID 36246628, 2022). "Furthermore, GBP5-knockdown OSCC cells showed decreased cell growth, G1/S arrest, decreased invasion/migration, and cancer stemness." (PMID 34439200, 2021).
cancer (continued). "GBP5, a member of the guanylate-binding protein (GBP) family, belongs to the INF-inducible guanosine triphosphate hydrolases (GTPases) superfamily and promotes tumorigenesis and cancer progression." (PMID 32639949, 2020). "In addition, in TCGA pan-cancer dataset, although the PBP signature overall was not prognostic, the higher expression levels of individual signature gene members, such as GBP5 and ATP6V1B2, were associated with better disease-specific survival." (PMID 37587913, 2023).
tumor (31 papers, 2018 to 2026). "In non-small cell lung cancer (NSCLC), GBP5 is upregulated in tumor tissues and is associated with a favorable prognosis." (PMID 40564939, 2025). "In ovarian cancer, GBP5 mutations impair immune efficacy, tilting the balance toward tumor escape by reducing T cell function and increasing PD-L1 expression." (PMID 40564939, 2025). "Previous studies have consistently demonstrated a positive association between GBP5 expression and M1-type macrophage activation 40, 43, which potentially possessed anti-tumor capability by promoting immune response and inhibiting tumor growth." (PMID 38817865, 2024). "In function, GBP5 is also associated with tumor immunity, which we demonstrated using a variety of methods, including GSEA enrichment analysis." (PMID 36246628, 2022). "Furthermore, GBP5 exhibits multiple splice variants, including hGBP5ta, which is specifically expressed in tumor tissues and demonstrates antigenicity, suggesting a potential role in tumorigenesis." (PMID 40788157, 2025). "Several mysteries still linger, such as whether the same conclusion can be reached in tumor cells, the specific form of pyroptosis GBP5 leads to, and the underlying mechanisms that remain to be uncovered." (PMID 38817865, 2024). "Moreover, the association of GBP5 expression with immune/stromal/Estimate scores and tumor purity was stronger than the other two genes." (PMID 33897701, 2021). "Further preclinical and clinical studies are needed to explore the impact of GBP5 on OC function and its tumor microenvironment." (PMID 40225866, 2025). "Several ISGs such as GBP family genes Gbp4 and Gbp5, Cxcl9, Oas2, and Stat1, were significantly downregulated in the old Tumor-3 subcluster." (PMID 41332581, 2025). "The ITRGM’s relationship with the tumor immune microenvironment was further validated in our experiments using pathology sections with GBP5, an important model gene, and CD8 IHC analysis." (PMID 39355255, 2024). "Collectively, elevated GBP5 expression in T cells potentially promotes T cell activation and infiltration, while simultaneously reducing the release of tumor-killing molecules, as evidenced by the downregulation of GZMB and IFNγ transcription in Jurkat cells." (PMID 38817865, 2024). "Patients with low tumor GBP5 expression and high stromal expression had significantly longer overall survival and recurrence‐free survival." (PMID 38978333, 2024). "Expression of GBP5 in the tumor and stroma correlated with immune cell infiltration of tumors and PD‐L1 expression in tumor and immune cells." (PMID 38978333, 2024). "Both the high GBP5 tumor and GBP5 stromal score groups had more tumor‐infiltrating immune cells in all subtypes than the respective low groups." (PMID 38978333, 2024). "In a preliminary IHC study with a small number of OSCC cases, GBP5 was found to be more strongly expressed in OSCC than in the normal oral epithelium, suggesting that GBP5 is associated with tumor‐infiltrating immune cells." (PMID 38978333, 2024). "Our results showed that high GBP5 scores in tumors and stroma correlated with high infiltration of all immune cells and high expression of PD‐L1 in both tumor and immune cells." (PMID 38978333, 2024). "The 5‐year survival rates were 100.0% in the GBP5 tumor (T) Low and GBP5 stroma (S) High group; followed by GBP5 (T) High and GBP5 (S) High group (80.8%); GBP (T) High and GBP5 (S) Low group (75.0%); and GBP5 (T) Low and GBP5 (S) Low group (67.1%)." (PMID 38978333, 2024). "Our research further validates this conclusion, suggesting a potential avenue for translating GBP5's proinflammatory expertise into the field of tumor therapy." (PMID 38817865, 2024). "Overall, our study reveals the relationship between GBP5 and tumor immunity and provides evidence for targeted GBP5 therapy." (PMID 36246628, 2022).
tumor (continued). "We found that GBP5 was positively correlated with immune score and stromal score, but negatively correlated with tumor purity in almost all tumors, which was validated in an additional cohort." (PMID 36246628, 2022). "In order to determine the immunological effects of GBP5 and find potential tumor types suitable for anti-GBP5 immunotherapy, a correlation between GBP5 expression with immune score, stromal score, and tumor purity was demonstrated." (PMID 36246628, 2022). "As for TME, GBP5 is generally positively correlated with immune score, the level of tumor-infiltrating immune cells and immune-related genes." (PMID 36246628, 2022). "In the present study, we found GBP5 to be highly expressed in tumor tissues by comparing the transcriptome profiles of the primary tumor and adjacent normal tissues from two paired OSCC tissues with NGS." (PMID 34439200, 2021). "Subsequently, gene expression levels of GBP5 were validated in normal and tumor tissues for 23 paired BMSCC patients and 14 paired TSCC patients by RT-PCR." (PMID 34439200, 2021). "Consistent with the results of previous in vitro studies, IHC staining of tumor sections showed higher levels of GBP5, p-Src, p-ERK1/2, and MMP3 in U87-GBP5 tumors relative to the control tumors." (PMID 33608513, 2021). "The results indicated that the expression of CASKIN1, EMR3, and GBP5 showed significant difference between the tumor and normal samples in both TCGA database and HPA." (PMID 33897701, 2021). "The protein expression levels of GBP5 in the tumor tissues exceeded that in CTAN from a total of 499 OSCC patients including 182 BMSCC, 245 TSCC, and 72 LSCC patients." (PMID 34439200, 2021). "After filtering genes by RPKM and fold change, we found that gene expression levels of GBP5 were increased by 9.10-fold and 6.59-fold in stages I (T1) and stages IV (T2) tumor tissues, respectively, compared with those in CTAN tissues (N1 and N2)." (PMID 34439200, 2021). "In contrast, the expression of both EMR3 and GBP5 were positively correlated with immune/stromal/Estimate scores, while negatively correlated with tumor purity." (PMID 33897701, 2021). "The tumor growth curve showed that GBP5 expression significantly promoted the growth of GBM cells during the period of 52 days in vivo." (PMID 33608513, 2021). "We also used the subcutaneous xenograft model in athymic nude mice to study the effects of GBP5 on GBM tumor growth in vivo." (PMID 33608513, 2021). "As expected, Western blot analysis of these tumor tissues showed that overexpression of GBP5 increased the levels of p-Src, p-ERK1/2, and MMP3." (PMID 33608513, 2021). "Human guanylate binding protein 5 (GBP5) belongs to the dynamin superfamily of interferon-gamma-inducible large GTPases3, which are considered as central orchestrators of neoplastic diseases immunity." (PMID 33608513, 2021). "Herein, next-generation sequencing analysis showed that the gene expression levels of GBP5 were significantly higher in OSCC tissues compared with those found in corresponding tumor adjacent normal tissues (CTAN) from two pairs of OSCC patients." (PMID 34439200, 2021). "CASKIN1 was overexpressed in tumor and its high expression was associated with poor OS, while high expression of EMR3 and GBP5 were associated with better survival." (PMID 33897701, 2021). "Compared with CTAN tissues, the gene expression levels of GBP5 were significantly increased in the tumor tissues of OSCC patients, including BMSCC (p < 0.001) and TSCC (p = 0.008) patients." (PMID 34439200, 2021). "The results showed that the adjacent normal brain tissues expressed low levels of GBP5, while 14 of 20 (70%) tumor samples expressed higher levels." (PMID 33608513, 2021). "Another four genes, GBP1, GBP5, LY6E and OAS2, have also been reported to be associated with a variety of other tumor progression." (PMID 33223511, 2020). "These were IRF1 and GBP5; genes related to transcriptional regulation, tumor response, inflammation, and innate immunity." (PMID 30408130, 2018).
tumor (continued). "However, it is important to consider that anti-tumoral pathways were not solely upregulated, and we observed an increase in the expression of genes such as GBP2 and GBP5, which are known to promote tumor progression and growth." (PMID 40498028, 2025). "Moreover, hub gene GBP5 acts as a tumor inhibitory factor and regulates the chemosensitivity of oxaliplatin, gemcitabine, and sorafenib in OC." (PMID 40225866, 2025). "High expression of GBP5 in tumor cells may affect the immune environment by promoting autophagy and modulating anti-tumor immune responses." (PMID 40225866, 2025). "In antiviral and anti-tumor immunity, GBP5 shows diverse roles." (PMID 40788157, 2025). "Similarly, in our model, GBP5 is a protective gene, with its upregulation observed in the tumor tissues of early-stage OC patients compared to late-stage patients." (PMID 40225866, 2025). "IFN‐γ, which regulates GBP5, is important for the development and differentiation of immune cells involved in anti‐tumor immune responses and immune editing, generally acting in a tumor suppressive manner in the tumor microenvironment." (PMID 38978333, 2024). "Our results suggest that the function of GBP5 in the tumor microenvironment may differ from that in the stroma." (PMID 38978333, 2024). "Consistently, GBP5 showed higher expression levels in tumor tissues relative to normal tissues." (PMID 39355255, 2024). "Correlations of tumor‐infiltrating immune cells with GBP5 expression in patients with OSCC." (PMID 38978333, 2024). "Therefore, we performed a hierarchical univariate Kaplan–Meier analysis using GBP5 tumor and GBP5 stromal scores." (PMID 38978333, 2024). "Future studies to elucidate the molecular mechanisms by which GBP5 affects the immunological tumor microenvironment may provide new therapeutic approaches for OSCC." (PMID 38978333, 2024). "Considering the immunogenicity of GBP5, we hypothesize that GBP5 can affect the prognosis by recruiting some tumor-suppressing immune cells." (PMID 36246628, 2022). "Given the good clinical and TME association of GBP5 in CRC, we believe that CRC may be a good tumor type for anti-GBP5 therapy." (PMID 36246628, 2022). "Meanwhile, the expression of GBP5 was also associated with M stage of tumor TNM stage in COAD, suggesting that GBP5 may influence CRC metastasis." (PMID 36246628, 2022). "Our results suggested that GBP5 has the potential to be biomarkers for certain macrophages or Tregs and may influence anti-tumor immunity through these immune cells." (PMID 36246628, 2022). "Moreover, the expression levels of CASKIN1, EMR3, and GBP5 genes were significantly correlated with immune/stromal/Estimate scores or tumor purity and multiple immune cell infiltration." (PMID 33897701, 2021). "Importantly, survival studies showed that knockdown of GBP5 significantly prolonged the survival time of mice bearing tumor (35 vs. 45 days, p = 0.0057." (PMID 33608513, 2021). "Consequently, targeting GBP5 in GBM cells resulted in impaired tumor growth and prolonged survival time of mice with GBM tumors." (PMID 33608513, 2021). "Moreover, GBP5 was highly elevated in all the Grade IV tumors, and 6 of 7 Grade III tumors, and 3 of 7 Grade II tumors, suggesting GBP5 expression is correlated with tumor grade." (PMID 33608513, 2021). "We found that GBP5 silencing significantly suppressed tumor growth and invasion." (PMID 33608513, 2021). "In addition, more F4/80/iNOS or F4/80/GBP5 double-positive cells could be observed in the tumor grafts of mice treated by DHA." (PMID 36034842, 2022). "Meanwhile, when co-cultured with GBP5-overexpressed HEY cells, the transcriptions of CCR5/7, which are crucial markers mediating T cell tumor infiltration 46, 47, were notably upregulated in T cell, simultaneously with a decrease in GZMB transcription." (PMID 38817865, 2024).